ATR (ATR checkpoint kinase)
Diseases named in the same sentence as ATR in open-access papers (continued):
Sharing a sentence is not in itself a finding about the gene and the disease.
esophageal cancer (6 papers, 2016 to 2024). A primary or metastatic malignant neoplasm involving the esophagus. "We then examined the effect of ATR KD on the growth of esophageal cancer cells using a proliferation assay." (PMID 36082941, 2022). "To determine the effect of ATR knockdown (KD) on the growth of esophageal cancer cells (KYSE150 and KYSE450), we established ATR stable KD cells and confirmed the expression of ATR protein by western blot." (PMID 36082941, 2022). "We next queried The Cancer Genome Atlas (TCGA) database to analyze the transcript expression profile of ATR in esophageal cancer and normal tissues based on sample types or tumor history." (PMID 36082941, 2022). "Based on “BRCAness” principle, our recent study found that methylation of NRN1 was a novel synthetic lethal marker for PI3K-Akt-mTOR and ATR inhibitors in human esophageal cancer." (PMID 34539742, 2021). "In other tumor sites, concurrent ATR inhibition has been shown in vitro to improve the response to cisplatin and radiation, both of which are key therapeutics in the treatment of esophageal cancer." (PMID 27839769, 2016). "To determine if inhibition of ATR using VX-970 inhibits ATR-mediated signaling in esophageal cancer we treated OE21 cells with the inhibitor and then exposed them to hypoxia (<0.1% O2) in order to induce ATR activity." (PMID 27839769, 2016). "Together, these data verify that VX-970 specifically and effectively inhibits hypoxia-induced ATR signaling in esophageal cancer cells." (PMID 27839769, 2016). "We have shown in three esophageal cancer cell lines (two SCC and one ACA) that the addition of the ATR inhibitor VX-970 increases loss of viability in response to cisplatin, carboplatin and radiation." (PMID 27839769, 2016). "Significant levels of tumor hypoxia suggest that esophageal cancers may also experience high levels of replication stress therefore making them sensitive to ATR inhibition." (PMID 27839769, 2016). "There is a strong scientific rationale for combining ATR inhibitors with platinum based chemotherapy and radiation, the standard therapies for esophageal cancer, although in vitro and in vivo experiments using esophageal cell lines have not been previously reported." (PMID 27839769, 2016). "Here, we demonstrate that the addition of the ATR inhibitor VX-970 both chemo and radio-sensitizes esophageal cancer cell lines in vitro and most importantly, that this translates to a significant tumor growth delay when combined with radiation in an in vivo model." (PMID 27839769, 2016). "Here, we tested the hypothesis that an ATR inhibitor, VX-970, used in combination with standard therapies for esophageal cancer could improve treatment outcome." (PMID 27839769, 2016). "Additionally, GSEA enrichments revealed the suppression of cell cycle and mitotic checkpoint regulatory (AURKB, PLK1, and E2F) and the DDR and DNA-repair (ATR, BARD1, and FANCONI) pathways by STL001 in esophageal cancer." (PMID 38697979, 2024).
nasopharyngeal carcinoma (6 papers, 2015 to 2025). A carcinoma arising from the nasopharyngeal epithelium. "In nasopharyngeal carcinoma, metformin also sensitized cells to radiation through DNA repair pathway modulation, upregulation of p-ATM and p-ATR and downregulation of ATM, ATR, p95/NBS1, Rad50, DNA-PK, Ku70 and Ku80." (PMID 35327549, 2022). "Our earlier study showed that ATR, a key kinase participant in single-stranded DNA damage response (DDR), was obviously activated by Epstein–Barr virus (EBV) in nasopharyngeal carcinoma (NPC)." (PMID 32917854, 2020).
pancreatic ductal adenocarcinoma (6 papers, 2021 to 2025). An infiltrating adenocarcinoma that arises from the epithelial cells of the pancreas. "As salvage and de novo pyrimidine pathways are suppressed by ATR blockade, combination of ATR inhibitor and OSU-03012, a DHODH inhibitor, reveals synergy against pancreatic ductal adenocarcinoma." (PMID 33971967, 2021). "In previous studies, we demonstrated that ATR/Chk1 inhibitors selectively enhanced F10 but not 5-FU cytotoxicity in human CRC cell lines, while inhibitors of the ATR/Chk1/Wee1 pathway enhanced CF10 but not 5-FU cytotoxicity in pancreatic ductal adenocarcinoma." (PMID 38611037, 2024).
prostate tumor (6 papers, 2020 to 2024). "We also found that somatic mutations in BRCA2, NEIL3, ATM, and ATR were associated with higher mutational burden in prostate tumors." (PMID 32300177, 2020). "We employed 14 patient-derived tumor graft models pancreatic, lung, and prostate tumor graft models harboring HR mutations (BRCA1/2, CHK1/2, ATM/ATR, PALB2, PARP1/2, RAD51, FANCA/B) to compare LP-184’s potency with PARPi olaparib." (PMID 38630886, 2024). "As with berzosertib, the recently reported ATR inhibitor M4344 demonstrated synergistic cytotoxicity in combination with topotecan or irinotecan in established cell lines, patient-derived prostate tumor organoids, and SCLC tumor xenograft models." (PMID 37637936, 2023). "In addition, ATR inhibitors induced an unstable state of PD-L1 in prostate tumor cells." (PMID 37305685, 2023).
sarcoma (6 papers, 2020 to 2025). A usually aggressive malignant neoplasm of the soft tissue or bone. "EWS–WT1, the unique oncogenic driver of desmoplastic small round cell tumors, confers sensitivity to PARP and ATR inhibitors, supporting the potential of these drugs in treating patients with this aggressive sarcoma subtype." (PMID 39412947, 2025). "Significance: EWS–WT1, the unique oncogenic driver of desmoplastic small round cell tumors, confers sensitivity to PARP and ATR inhibitors, supporting the potential of these drugs in treating patients with this aggressive sarcoma subtype." (PMID 39412947, 2025). "We show that late-generation Pot1b−/− sarcoma telomeres contain G-quadruplexes, which activate an ATR-dependent DDR to recruit telomerase to hyper-elongate telomeres." (PMID 37560909, 2023). "In contrast, ATRX knockdown in the ALT-negative, NF1-associated sarcoma line JHH-CRC65 did not increase sensitivity to either ATR inhibition or temozolomide treatment." (PMID 35740680, 2022). "Serial transplantation of Pot1b−/− sarcomas into SCID mice has uncovered a role for POT1b in the regulation of telomere elongation and repression of an ATR-dependent DDR." (PMID 37560909, 2023). "Further studies are needed to understand more in depth how is ATR and CHK1 signaling activated in unperturbed sarcoma cells." (PMID 32366852, 2020). "Interestingly, we found that all the cell lines tested here displayed some degree of basal ATR activation as illustrated by the constitutive phosphorylation of CHK1 in sarcoma cells in the absence of treatment/damage induction." (PMID 32366852, 2020).
gynecological cancers (5 papers, 2021 to 2024). "The ongoing phase 2 study ATARI is investigating the impact of olaparib (PARPi) monotherapy and in combination with an ATR inhibitor drug (AZD6738) in gynecological cancers and compares tumors with and without ARID1A loss (NCT04065269)." (PMID 38184614, 2024). "The results of the ATARI trial will provide the first indication of whether there is clinical activity of ATR inhibitors in clear cell carcinomas and other rare gynecological cancers according to ARID1A status." (PMID 34518240, 2021). "For instance, ATARI trial is a multicenter, international, phase II study (NCT0405269) testing the ATR inhibitor ceralasertib as a single agent and in combination with olaparib in ARID1A gynecological cancers." (PMID 37711591, 2023). "The cohort of non-clear cell, rare gynecological cancers provides the opportunity to assess the combination of ATR and PARP inhibition in a further cohort of patients with limited treatment options." (PMID 34518240, 2021). "The ataxia telangiectasia and Rad3-related (ATR) inhibitors, DNA-dependent protein kinase (DNA-PK) inhibitors, WEE1 inhibitors, and checkpoint kinase 1/2 (CHK1/2) inhibitors have shown promising clinical results recently, and a number of ongoing trials are focusing on gynecologic cancers." (PMID 34680987, 2021).
Obesity (5 papers, 2022 to 2024). Accumulation of substantial excess body fat. "We envisage a scenario in which obesity-associated meta-inflammation impairs AMT/ATR activation with dysregulated downstream DNA damage repair." (PMID 39092995, 2024). "Collectively, these results suggest a problem with activation of ATM/ATR-mediated DNA damage response in obesity." (PMID 39092995, 2024). "However, there was a tendency towards elevated levels of phosphorylated ATM (pATM), ATR (pATR), H2AX (γ-H2AX) and KAP1 (pKAP1) in subjects with obesity." (PMID 39256343, 2024). "The phosphorylation levels of ATM and ATR, as well as those of their recognized downstream effectors, histone H2AX and KAP1, were significantly higher in the VAT biopsies of subjects affected by obesity compared to NW individuals." (PMID 39256343, 2024).
soft tissue sarcoma (5 papers, 2020 to 2024). A malignant neoplasm arising from muscle tissue, adipose tissue, blood vessels, fibrous tissue, or other supportive tissues excluding the bones. "The objective of this study is to evaluate the pre-clinical activity of ATR inhibition in soft tissue sarcomas (STS)." (PMID 32366852, 2020). "The combination of ATR inhibitor and chemotherapy is beneficial in pre-clinical models of soft-tissue sarcoma and deserves further exploration in the clinical setting." (PMID 32366852, 2020). "Targeting ATR in Soft-tissue Sarcomas (TARSARC) is an ongoing Phase 2 randomised non-comparative trial of gemcitabine versus gemcitabine combined with the ATR inhibitor berzosertib in patients with advanced or metastatic leiomyosarcoma." (PMID 39796641, 2024).
Werner syndrome (5 papers, 2010 to 2024). "First, we examined CHK1 phosphorylation at Ser345 in an isogenic pair of uncorrected and WRN wild-type-corrected (WSWRN) SV40-transformed Werner syndrome (WS) fibroblasts, in which ATM (ATMi), ATR (ATRi) or both (ATMi/ATRi) were chemically inhibited." (PMID 30657978, 2019). "Previous DCC studies of Werner syndrome and control cells suggested that DCC defect per se is not sufficient to cause significant genomic instability, but requires absence or dysfunction of "caretaker" genes such as ATR, BRCA1 or WRN." (PMID 21824431, 2011).
clear cell ovarian cancer (4 papers, 2023 to 2025). "Additionally, this mutation enhances sensitivity to ATR inhibitors in ovarian clear cell carcinoma cells." (PMID 40251453, 2025).
dwarfism (4 papers, 2017 to 2022). "Mutations in ATR can cause Seckel syndrome 1, which is characterized by mental retardation and proportional dwarfism." (PMID 29567674, 2018).
mantle cell lymphoma (4 papers, 2018 to 2025). Mantle cell lymphoma is a rare form of malignant non-Hodgkin lymphoma affecting B lymphocytes in the lymph nodes in a region called the ``mantle zone''. "Targeting ATR can be taken in to consideration, where single-agent ATR inhibitors revealed to be potential therapeutic agent for mantle cell lymphoma with ATM-deficiency." (PMID 30975222, 2019). "Cotreatment of mantle cell lymphoma (MCL) cells with AF and ABT-888 (PARPi) increases synergistically the apoptosis of ATM-proficient MCL cells, with increased γ-H2AX foci induction in the DNA and depletion of p-Chk1 (a downstream target of ATR signaling)." (PMID 29770165, 2018).
metastatic disease (4 papers, 2019 to 2024). "Strikingly, ATM is the only cell cycle checkpoint kinase gene enriched for mutation in the primary setting, as both CHEK2 (P = 0.001) and ATR mutations (P = 0.0002) are enriched in metastatic disease." (PMID 37390209, 2023). "While ATR inhibition or ablative radiotherapy alone had a limited effect on lung tumor progression, the combination of ATR inhibition and ablative radiotherapy significantly reduced the metastatic tumor burden in non-irradiated lung regions (P < 0.05) than that in the control group." (PMID 39487895, 2024).
rectal cancer (4 papers, 2022 to 2023). A primary or metastatic malignant neoplasm that affects the rectum. "Co-IHC staining of ATR together with the scaRNA2 FISH probe revealed colocalization of scaRNA2 and ATR in rectal cancer tissues." (PMID 37775817, 2023). "The exact mechanisms through which PD-L1 leads to immune evasion of rectal cancer upon radiation are still under debate; however, it has been suggested that activation of the ATR signaling pathway in rectal cancer cells could play a major role, preventing their phagocytosis by APCs." (PMID 37958298, 2023).
xeroderma pigmentosum (4 papers, 2021 to 2025). Xeroderma pigmentosum (XP) is a rare genodermatosis characterized by extreme sensitivity to ultraviolet (UV)-induced changes in the skin and eyes, and multiple skin cancers. "Moreover, ATM and ATR mediate the increase in DDB2 (Damage Specific DNA Binding Protein 2) and XPC (xeroderma pigmentosum, complementation group C)." (PMID 34356109, 2021).
Alzheimer disease (3 papers, 2020 to 2023). A progressive, neurodegenerative disease characterized by loss of function and death of nerve cells in several areas of the brain leading to loss of cognitive function such as memory and language. "Previous studies indicated that ATR is promising as a potential drug candidate for the treatment of Alzheimer’s disease (AD), depression, or ulcerative colitis." (PMID 37007031, 2023). "In view of good pharmacological activities, ATR is expected to be a potential drug candidate for the treatment of Alzheimer’s disease, depression, or ulcerative colitis." (PMID 37007031, 2023).
Anxiety (3 papers, 2015 to 2022). Intense feelings of nervousness, tension, or panic often arise in response to interpersonal stresses. "Even more unexpectedly, the reduction of adult neurogenesis by deletion of the cell cycle checkpoint gene ATR produces an anxiolytic phenotype in marble burying, novelty-induced hypophagia, and zero-maze tests, while enhanced adult neurogenesis by voluntary exercise increases anxiety." (PMID 26464972, 2015). "Thus, it appears that aberrant WM microstructure in the genu of the CC and bilateral ATR uniquely contributes to difficulties in emotion regulation and irritability, but not anxiety or general impairment." (PMID 31883419, 2020).
autosomal recessive primary microcephaly (3 papers, 2016 to 2021). Autosomal recessive primary microcephaly (MCPH) is a rare genetically heterogeneous disorder of neurogenic brain development characterized by reduced head circumference at birth with no gross anomalies of brain architecture and variable degrees of intellectual impairment. "Exome analysis also showed heterozygous variants in three genes, ATR, MCPH1 and BLM, which are known causes of autosomal recessive primary microcephaly." (PMID 28464862, 2017). "Similarly, genetic disorders characterized by microcephaly, such as autosomal recessive primary microcephaly (MCPH) and ATR-Seckel syndrome, are recognized to involve defects in centrosome maintenance." (PMID 27367050, 2016).
B cell lymphoma (3 papers, 2016 to 2025). "Inhibition of ATR reverses the dark zone signature linked to T-cell exclusion in aggressive B-cell lymphomas." (PMID 40674145, 2025). "In line with previous findings, we found that NL101 induces DNA damage in B cell lymphoma as ATR, ATM, CHK1 and CHK2 phosphorylation increase." (PMID 33537096, 2021). "We therefore examined the therapeutic efficacy of combining inhibition of ATM/ATR signaling with CX-5461 in MYC driven B-cell lymphomas (Eμ-Myc)." (PMID 27391441, 2016). "Furthermore, tumours bearing high levels of oncogene-induced DNA damage response (DDR), such as MYC driven murine lymphoma (Eμ-Myc) and human B-cell lymphomas, are sensitive to therapeutic targeting of DNA-dependent Protein Kinase (DNA-PK) and ATM/ ATR." (PMID 27391441, 2016).
Bloom syndrome (3 papers, 2017 to 2025). Bloom syndrome (BSyn) is a rare chromosomal breakage syndrome characterized by a marked genetic instability associated with pre- and postnatal growth retardation, facial sun-sensitive telangiectatic erythema, increased susceptibility to infections, and predisposition to cancer. "BLM helicase, the human orthologue of SGS1 mutated in the cancer-prone Bloom syndrome, interacts with stalled replication forks and is phosphorylated in an ATR-dependent manner following dNTP depletion, suggesting possible functional crosstalk between ATR and BLM at stalled replication forks." (PMID 28220209, 2017).
bone tumor (3 papers, 2020 to 2022). "In accordance with this, we found that MTHFD2 inhibitors TH7299 and TH9619 are synergistic when combined with ATR inhibitors VE-821 or VE-822 in both AML HL-60 and THP-1 cells, as well as in bone cancer cell lines U2OS and TC71, increasing apoptosis in a time- and dose-dependent manner." (PMID 35228749, 2022).
cholangiocarcinoma (3 papers, 2021 to 2025). A carcinoma that arises from the intrahepatic biliary tree (intrahepatic cholangiocarcinoma) or from the junction, or adjacent to the junction, of the right and left hepatic ducts (hilar cholangiocarcinoma). "We then selected the chondrosarcoma cell line SW1353, which harbors an IDH2 mutation (R172S/+), as well as the cholangiocarcinoma cell line RBE, which harbors an IDH1 mutation (R132S/+) for combination ATR and PARP inhibitor studies." (PMID 34027408, 2021). "For example, distinct peptide mass fingerprints (PMFs) were identified for early versus late recurrence in cholangiocarcinoma (CCA), where peptides such as KNTC1, DCLK1, ALG10, ATR, and BLM were associated with early recurrence, while SERPINA1, TGFB2, and SERPING1 were implicated in late recurrence." (PMID 41008874, 2025). "To this end, we selected several IDH1/2-WT and -mutant cholangiocarcinoma, fibrosarcoma and chondrosarcoma cell lines, and we first tested monotherapy PARP and ATR inhibitor sensitivity in order to identify the appropriate dose ranges for the combination drug studies." (PMID 34027408, 2021).
chondrosarcoma (3 papers, 2021 to 2025). A malignant cartilaginous matrix-producing mesenchymal neoplasm arising from the bone and soft tissue. "“Although clinical data specifically in ALT-positive GBM or chondrosarcoma remain limited, preclinical studies have shown strong ATR dependency in ALT and ATRX-deficient settings." (PMID 41148828, 2025). "In slow-growing and metabolically constrained tumors such as GBM and chondrosarcoma, chronic replication stress places the DNA damage response near its tolerance threshold; thus, additional ATR inhibition precipitates replication collapse and cell death, amplifying the therapeutic effect." (PMID 41148828, 2025). "Recent studies suggest that ataxia telangiectasia and rad3 related (ATR) inhibitor and disulfiram enhance the radiosensitivity in chondrosarcoma, which may reduce radiological side effects." (PMID 37669996, 2023).